KIT (KIT proto-oncogene, receptor tyrosine kinase)
Diseases named in the same sentence as KIT in open-access papers (continued):
Sharing a sentence is not in itself a finding about the gene and the disease.
tumor (continued). "Immunohistochemically, the tumor cells showed strong punctate staining for cytokeratin, patchy but strong membranous reactivity for LCA and CD43, and positivity for TTF-1 and P63, and CD117 (KIT)." (PMID 38649942, 2024). "Based on the analysis on single-cell data, the tumor cells can be divided into six categories, i.e., PDGFRA_fib, BASP1_fib, DUSP1_fib, IDO1_fib, KITlow DOG+ SMA+_fib, and KIT-_fib, of which BASP1_fib and DUSP1_fib are the most common cell subpopulations in GIST." (PMID 38443340, 2024). "These included positive readings for ER (95%), PR (5%), cytokeratin-7 (CK-7), and GATA binding protein 3 (GATA-3), while P63 and KIT (CD117) were absent in the tumor cells and HER-2/neu score was zero." (PMID 39125514, 2024). "The biomarkers identified in the T3 subtype include MSLN and CD117 (KIT), which have been reported in TC and other advanced tumor cells, and CCL20 which has not been reported in TC." (PMID 39258580, 2024). "Quantification of immunofluorescence signal in areas of tumor and normal duct showed higher c-KIT positivity in normal duct compared to luminal tumor, but higher c-KIT positivity in basal tumor compared to normal duct." (PMID 39478117, 2024). "Considering the tumor’s response to therapies, which varies based on its molecular environment, molecular profiling also plays a crucial role, and it is targeted mainly towards BRAF, NRAS, and c-KIT genes." (PMID 39519055, 2024). "Tumor profiling in GISTs is not performed routinely for patients outside of testing for KIT and PDGFRA." (PMID 38885448, 2024). "Previous studies have demonstrated the important tumour-suppressive role of miR-193b-3p, as it targets several members of the RAS-RAF-MEK-ERK pathway which is crucial for cell cycle and proliferation, as well as c-KIT and the MYB oncogene." (PMID 39796140, 2024). "KIT and ERBB3 receptors regulate cellular growth and differentiation, driving tumor proliferation." (PMID 39273340, 2024). "The significance of these findings for cancer immunotherapy seems essential, as the pharmacological inhibition of c-KIT and OX40L, or gene ablation, could be further tested for the enhancement of the anti-tumor activity of NK cells in response to rituximab." (PMID 39201666, 2024). "The tumour cells showed diffuse immunoreactivity for S-100 and SOX10 proteins, but no immunostaining was observed for smooth muscle actin (alpha-SMA) and KIT (CD117)." (PMID 38201647, 2024). "In our study, compared to GISTs without KIT exon 11 deletion, GISTs with KIT exon 11 deletion usually exhibit characteristics such as a larger tumor maximum diameter, an ill-defined tumor margin." (PMID 37645430, 2023). "If HαT testing is negative, the patientś peripheral blood leukocytes should then be tested for KIT D816V and the patient should be considered for a bone marrow (BM) biopsy to rule out SM and other BM neoplasms." (PMID 37572755, 2023). "Next-generation sequencing (NGS) assays indicated that the tumor lacked KIT/PDGFRA/SDH/RAS-P (RAS pathways, RAS-P) mutations, thereby classifying this patient as quadruple WT GIST (qGIST)." (PMID 38023229, 2023). "In contrast, drugs with molecular targets: ABL, KIT, PDGF, SRC, and VEGFR were enriched in the drug clusters showing a strong effect on tumor cell intravasation with less impact on cell invasion or cell proliferation, of which, Imatinib, a multi-kinase inhibitor targeting BCR-ABL/PDGFR/KIT." (PMID 38239643, 2023). "Since the miR-29b/Sp1 feedback loop is deregulated in other hematological malignancies, like KIT-driven AML, it is tempting to speculate that G-1 might trigger anti-tumor effects also in these cancers." (PMID 37759449, 2023).
tumor (continued). "Kit (also known as c-KIT), one of the type III tyrosine kinase receptors, plays a critical role in numerous cellular processes, including cell survival, proliferation, growth and development, and neoplasia." (PMID 36675807, 2023). "For example, targeting most IGCTs with upregulated KIT/RAS/MAPK pathway and/or PI3K/AKT/mTOR pathway, designing inhibitors for these pathways may be a new idea for developing tumor-targeted drugs." (PMID 38012690, 2023). "Among them CCNB1, MIF, PLA2G4A may be regarded as oncogenes, whereas RNASE3, APOE, FOXO1, KIT, and EGR1 may be tumor suppressor genes." (PMID 37065484, 2023). "Therapeutic strategies that target insulin/AMPK signaling and/or multi-TKI inhibitors that target ROS, ALK, KIT, FAK, TIE2, SRC, etc., may specifically target the tumor biology of these poorest-prognosis patients." (PMID 38086377, 2023). "However, c-KIT expression was shown to be expressed in all compartments of c-HCC-CCA in a case report, strongly suggesting that this tumor was entirely derived from liver stem cells/progenitor cells." (PMID 36672443, 2023). "One of these is regorafenib, an oral multikinase inhibitor (MKI) that blocks the activity of multiple protein kinases involved in oncogenes (KIT, RET, RAF, and BEAF), tumor angiogenesis (VEGFR1, VEGFR2, VEGFR3, and TIE2), and the tumor microenvironment (PDGFR and FGFR)." (PMID 37142953, 2023). "Immunostaining of the tumor cells showed positive staining for KIT and DOG1 and negative staining for S100 and desmin." (PMID 37789344, 2023). "Thus, SH3BP2 silencing decreased oncogenic KIT/PDGFRA levels, reduced MITF levels, led to apoptosis in vitro, and decreased tumor growth in vivo." (PMID 36834926, 2023). "Regorafenib is an oral inhibitor of several kinases involved in tumor angiogenesis (VEGFR1-3 and TIE2), oncogenesis (KIT, RET, RAF1, and BRAF), and in the interaction between tumor and microenvironment (PDGFR, FGFR), and tumor immunity (colony-stimulating factor 1 receptor [CSF1R])." (PMID 37071295, 2023). "Immunohistochemical evaluation of the biopsy specimen revealed c- KIT expression, but no data on the molecular features of the tumour were available." (PMID 37318715, 2023). "In this group of patients, mutations in IDH2 (n = 3), KRAS (n =3), KIT (n = 3), and SETD2 (n = 1) were identified at low AF (median, 0.86%; range, 0.68 to 2.9%), though the corresponding mutation in the primary tumor was not known." (PMID 35273917, 2022). "Inhibition of KIT activity by different agents, such as specific RTK inhibitors, targeted antibodies, SCF-conjugated bacterial toxins, and interfering RNAs, leads to decrease in NB cells proliferation rate and tumor growth in vivo." (PMID 35887076, 2022). "When WT KIT/PDGFRA GISTS are suspected, intensive genetic analysis is recommended, and obtaining a better molecular characterization of these tumours might reveal novel therapeutic avenues." (PMID 35978808, 2022). "Moreover, we detected five different gene amplifications in two different tumor specimens, including MYC (n = 2), PDGFRA, KIT, KRAS, and RICTOR." (PMID 35454843, 2022). "However, we and others have previously shown that signaling by (wild-type) KIT maintains stem-like cancer cells in CRC and is required for colony- and tumor-forming potential." (PMID 35842424, 2022). "In MM, tumor plasma cells with a mature phenotype gain a certain degree of phenotypic plasticity by expressing specific stem cell progenitor markers, such as SOX2, MAGE, CD117 (KIT), and Nestin." (PMID 35454868, 2022). "In the KIT‐T670I/BaF3‐ and GIST‐T1‐T670I‐inoculated mouse models, 100 mg·kg−1 nintedanib nearly completely suppressed tumour growth, with TGI values of 93.3% and 80.3%, respectively, while imatinib showed a limited effect on tumour growth at the same doses." (PMID 35194937, 2022). "Among the genes screened out by ChIP-seq of GIST tumour samples and cell lines, OSR1 was hypothesized to bind to the c-KIT locus by ATAC sequencing." (PMID 36076237, 2022).
tumor (continued). "It was proposed that the KIT-SCF interplay is involved in progression of NB and could be a potential target for tumor therapy." (PMID 35887076, 2022). "The effect of dovitinib on the tumor volume in our study was most likely attributed to the inhibition of KIT which resulted in an almost complete absence of proliferation." (PMID 35625872, 2022). "Lenvatinib inhibits VEGF receptors 1–3, platelet-derived growth factor receptor-α, fibroblast growth factor receptors (FGFR) 1–4, KIT, and RET, among which inhibition of VEGF receptor 2 contributes to the major pharmacological effect, including the inhibition of tumor neoangiogenesis." (PMID 35089453, 2022). "Furthermore, the clinical rationale of molecular tumor characterization regarding BRAF, KIT or NRAS, as well as the therapeutic value of immunotherapy, chemotherapy and targeted therapy, has not yet been deeply explored and clearly established in MM." (PMID 35052829, 2022). "Cluster 1 was characterized by upregulation of tumor-suppressing genes: HNF1B, CCNDBP1, PATJ, EPB41L3, MARVELD2, PTEN in conjunction with cell-cycle genes – GSPT1, GPR19, EAPP, KIT, CDKL1, and stem cell markers – RBBP5, NANOG, NCSTN, ERG, including quiescent stem cell markers—FOXP1, SMARCA2." (PMID 36348001, 2022). "Regorafenib is an oral tyrosine kinase inhibitor that blocks multiple protein kinase activities, including proteins involved in the regulation of oncogenesis (KIT, RET, RAF-1 and BRAF), tumour microenvironment (PDGFR and FGFR) and tumour angiogenesis (VEGFR1, 2 and 3 and TIE-2)." (PMID 35326702, 2022). "DOG-1 immunostain showed moderately intense cytoplasmic positivity in the tumor cells confirming the diagnosis of GIST, spindle cell type, moderate risk category However, CD117 (c-KIT) immunostain was negative." (PMID 34139427, 2021). "Analogous to NF1, around 30% of MM cases with SPRED1 inactivation simultaneously exhibit KIT alterations, suggesting that SPRED1 inactivation may be in collaboration with other oncogenic events to stimulate tumor development." (PMID 34350118, 2021). "The CAFs expressed FSP1, but not GIST markers by IF staining and immunoblotting analysis, whereas GIST-T1 (T1) (KIT exon 11 mutant) and primary tumor cells (from a KIT-expressing PDGFRA mutant GIST) did not express FSP1." (PMID 33603171, 2021). "Interestingly, MK-1775 alone had a considerable effect on tumor volume compared with vehicle in only the PDGFRA-driven xenografts, indicating inherent cell cycle differences in KIT-driven versus PDGFRA-driven GISTs." (PMID 33320833, 2021). "Moreover, CM from these CAF cultures increased T1 proliferation, while these effects were abrogated by PDGFC neutralizing antibody, suggesting that PDGFC secretion from CAF lines isolated from KIT and PDGFRA mutant GISTs modulates tumor cell growth." (PMID 33603171, 2021). "Indeed, sorafenib inhibits the phosphorylation of various targets present in the signaling pathways of both tumor cells (i.e., CRAF, BRAF, V600E BRAF, c-KIT, and FLT-3) and in the tumor-endothelial cells (i.e., CRAF, VEGFR-2, VEGFR-3, and PDGFR-β)." (PMID 34681219, 2021). "Correlation analysis between c-KIT staining and tumor size or duration of symptoms were not statistically significant (p value = 0.6912 and 0.1474 respectively, analyzed using GraphPad software)." (PMID 34439864, 2021). "Moreover, c-KIT-targeted NIR-PIT using anti-CD117 antibody induced acute necrotic cell death and was very effective in a GIST tumor model." (PMID 34064074, 2021). "In solid tumors the main target of these drugs are oncoproteins crucial for tumor maintenance and survival such as epidermal growth factor (EGFR), B-Raf proto-oncogene/serine/threonine kinase (BRAF), proto-oncogene c-Kit (KIT), human epidermal growth factor receptor 2 (HER2)." (PMID 32218226, 2020). "The pathological examination showed KIT (+), CD34 (+), desmin (−), and S-100 (−) in the tumor." (PMID 32146688, 2020).
tumor (continued). "Studies also suggested that activation of c-KIT enhances the expression of VEGF that can be suppressed by imatinib, an inhibitor of c-KIT in gastrointestinal stromal tumor cells, which thereby has an impact on tumor angiogenesis." (PMID 32855630, 2020). "Some of these proteins were tumor suppressors, including Rb, FOXO3, and p27, and many proteins were kinases and involved in the regulation of cell proliferation, differentiation, and apoptosis, such as c-KIT, AKT, EGFR, MAPK1/3, PRKCA, SRC, ACVRL1, and JNK2." (PMID 32917965, 2020). "The remaining 10% of GIST, have no KIT or PGGFR mutations and comprise a heterogeneous molecular group of tumours." (PMID 31911828, 2020). "The tumor cells were immunohistochemically positive for KIT, CD34, and discovered on GIST-1 (DOG-1) but negative for S-100 and alpha-SMA." (PMID 32703220, 2020). "The oncogenic reliance of GISTs upon mutated KIT/PDGFRA is emphasized by their sensitivity to imatinib mesylate (IM), a tyrosine kinase inhibitor (TKI) that targets both KIT and PDGFRA kinase activity, leading to substantial tumor shrinkage with durable responses in most patients." (PMID 30867899, 2019). "The pathological findings were compatible with GIST and the tumor consisted of spindle cells with positive staining for KIT, CD34, and DOG1 and negative or weak staining for desmin and S-100 protein." (PMID 30943904, 2019). "This network demonstrates that 61 exosomal molecules may affect tumor progression through pathways controlled by key components including MET, Ras, RAF1, Mek, ERK1/2, MITF, BCL2, PI3K, Akt, mTOR, PD-1, KIT, JAK STAT3, or ETS1." (PMID 31681332, 2019). "c-KIT, FLT-3 and RET are located on the tumour cell surface." (PMID 31547602, 2019). "Simon and his colleagues found that DOG1 regulated the anti-angiogenic factor IGFBP5, leading to the modulation of IGF/IGFR signaling in the tumor microenvironment, which did not involve KIT expression and KIT-dependent pathways." (PMID 31100836, 2019). "Secondly, data on TKIs used and pathologic outcomes, such as tumour necrosis, ulceration, type of PDGFR or KIT mutations, are not available in the SEER database." (PMID 29487722, 2018). "Moreover, the expression of human CD45+c-KIT+ cells, human CD45+HSP90+ cells and human HSP90β mRNA in tumor tissues isolated from the mice were significantly decreased." (PMID 29127384, 2017). "Inhibition of c-KIT using lentiviral short hairpin RNA in human PC cell lines reduced tumour growth and increased the incidence of metastasis, suggesting a key role for c-KIT in intraosseous tumour growth in xenografts model." (PMID 29207991, 2017). "Furthermore, c-KIT is a mutagenic effective proto-oncogene with a stem-cell factor (SCF) as a ligand, and it leads to tumor growth through impairment of cellular growth regulation." (PMID 28301608, 2017). "Regorafenib is a potent oral inhibitor of multiple kinases which might be involved in tumor angiogenesis (VEGFR-1, -2, -3, Tie-2), oncogenesis (KIT, RET, RAF-1, BRAF, BRAFV600E), and tumor niche formation (PGDFR, FGFR)." (PMID 29371921, 2017). "Per report, the tumor exhibited weak and focal positivity for CD117 (KIT), vimentin and calretinen, and was negative for SMA, S100, CD34, and desmin." (PMID 28768491, 2017). "Among these genes, many are involved in tumour suppression [e.g. RB1], apoptosis [e.g. BCL2L1], the cell cycle [e.g. CCND1, CCND2] or protein kinases [e.g. KIT, GSK3‐β]." (PMID 28539478, 2017). "In the present study, regardless of the tumor's location, the two epithelioid-type GISTs were c-KIT negative." (PMID 28915565, 2017). "This tumor shows positive immunohistochemical reactions for α-smooth muscle actin and desmin and a negative reaction for KIT (CD117)." (PMID 28111536, 2017). "The PC1 cell line is from a primary tumour showing no c-KIT immunoexpression and presenting RQ 0.091 in RT-qPCR analysis." (PMID 29207991, 2017).
tumor (continued). "p55PIK and KIT protein expression, and NF-κB p65 (Ser536) phosphorylation were also strongly increased, even in IMA-resistance tumor samples from GIST patients with secondary mutations (No. 3 and 5, marked with #)." (PMID 26587973, 2016). "Whereas the tumor was negative for c-KIT, it was strongly positive for PDGFR-α and PDGFR-β, designating this receptor as a potential therapeutic target in LGESS and warranting further research." (PMID 26576131, 2015). "Staining of the GIST from the patient’s earlier resection confirmed complete absence of MAX and strong plasma membrane staining for KIT in the tumor." (PMID 26555092, 2015). "Even though c-KIT expression is not required for the tumor formation, serial transplantation assays showed that c-KIThigh cells are more aggressive and induce tumors 9-fold more efficiently than c-KIT−/low cells." (PMID 26682270, 2015). "Regorafenib (BAY 73-4506) binds to and inhibits VEGFR-1, - 2 and -3, and tumor cell signaling kinases (RET, KIT, PDGFR, and Raf), which may result in the inhibition of tumor angiogenesis and tumor cell proliferation." (PMID 25884155, 2015). "Those genes showing high expression in CXXC5HIGH primary human AML cells and being significantly altered (i.e. increased) after CXXC5 knockdown included one potential tumor suppressor (TSC22), the cytokine Angiopoietin 1, a selenium transport protein and the hematopoietic growth factor receptor KIT." (PMID 25605239, 2015). "Even in lesions with double mutations that show extreme imatinib resistance, imatinib may weakly inhibit the downstream signaling of KIT or PDGFRA and slows tumor progression." (PMID 24587795, 2014). "Sorafenib is an oral multikinase inhibitor that inhibits the Ras/Raf/MAPK signaling pathway, as well as platelet-derived growth factor receptors-α and β, VEGFRs-1, 2 and 3 and c-KIT and FLT3 kinases, to prevent tumor growth by antiangiogenic, antiproliferative and/or proapoptotic effects." (PMID 24940450, 2014). "We hypothesize that in dogs the more aggressive diffuse type of tumor, like in human CSEM, expresses c-KIT more frequently because of its different cellular origin than the less invasive intratubular SEM." (PMID 25096628, 2014). "Histologically the tumor tissue had strong KIT and DOG-1 staining (data not shown), consistent with GIST." (PMID 24507750, 2014). "Regorafenib shows significant anti-tumour effects in this model, which seem independent of KIT inhibition." (PMID 25132955, 2014). "For example, miR-221 acts as an oncogene in liver cancer by downregulating the expression of the tumor suppress or phosphatase and tensin homolog (PTEN), but it acts as a tumor suppressor in erythroblastic leukaemia by reducing the expression of the KIT oncogene." (PMID 25243170, 2014). "The buttock tumor cells were negative for c-KIT, but diffusely positive for platelet-derived growth factor receptor-α (PDGFRA) and were definitively diagnosed as a skeletal muscle metastasis of the primary small intestine GIST." (PMID 25037940, 2014). "The gastric KS (case 12) presented a focal c-KIT expression in tumor cells, but the endothelial cells were negative." (PMID 23936513, 2013). "The positivity of spindle-shaped KS tumor cells for CD105 and COX-2, first reported in our study, in correlation with CD34, VEGF, SMA, and c-KIT positivity, seems to suggest that KS, similar to other fibroblastic tumors, originates from the PMCs and is related to the VEGF secretion." (PMID 23936513, 2013). "Co-culture of anti-KIT dTc with KIT- control tumor cells did not result in significant IFNγ production (data not shown)." (PMID 23433424, 2013). "In the plaque stage (cases 7, 8, and 10), c-KIT was focally observed in tumor cells and present or absent in the endothelium." (PMID 23936513, 2013).